FICD (FIC domain protein adenylyltransferase)
Description:
Protein that can both mediate the addition of adenosine 5'-monophosphate (AMP) to specific residues of target proteins (AMPylation), and the removal of the same modification from target proteins (de-AMPylation), depending on the context (By similarity). The side chain of Glu-231 determines which of the two opposing activities (AMPylase or de-AMPylase) will take place. Acts as a key regulator of the ERN1/IRE1-mediated unfolded protein response (UPR) by mediating AMPylation or de-AMPylation of HSPA5/BiP. In unstressed cells, acts as an adenylyltransferase by mediating AMPylation of HSPA5/BiP at 'Thr-518', thereby inactivating it (By similarity). In response to endoplasmic reticulum stress, acts as a phosphodiesterase by mediating removal of ATP (de-AMPylation) from HSPA5/BiP at 'Thr-518', leading to restore HSPA5/BiP activity (By similarity). Although it is able to AMPylate RhoA, Rac and Cdc42 Rho GTPases in vitro, Rho GTPases do not constitute physiological substrates.
Synonyms: HIP13; HYPE; SPG92; UNQ3041
Tractability: Small molecule: a structure with a bound ligand is known. Antibody: UniProt predicts a signal peptide or a membrane-spanning region.
Gene: Protein-coding gene on chromosome 12 (108,513,710 to 108,525,837, forward strand). Ensembl gene ENSG00000198855.
Subcellular location: Endoplasmic reticulum membrane
Subcellular location (Human Protein Atlas): Nucleoplasm
Gene Ontology:
Molecular function: AMPylase activity; ATP binding; Hsp70 protein binding; identical protein binding; protein adenylylhydrolase activity; protein binding; protein homodimerization activity; protein-folding chaperone binding
Biological process: protein adenylylation; regulation of IRE1-mediated unfolded protein response; response to endoplasmic reticulum stress; negative regulation of GTPase activity; protein deadenylylation
Cellular component: endoplasmic reticulum; endoplasmic reticulum membrane
Genetic constraint (gnomAD): Loss-of-function variants: 13 observed, 27.68 expected, observed/expected ratio (o/e) 0.47, 90% interval 0.31 to 0.75. The upper end of that interval is the gene's LOEUF score, 0.75, which puts it in group 3 of 6, group 1 being the genes least tolerant of losing a copy. Missense variants: 576 observed, 630.85 expected, observed/expected ratio (o/e) 0.91, 90% interval 0.85 to 0.98. Synonymous variants: 268 observed, 265.99 expected, observed/expected ratio (o/e) 1.01, 90% interval 0.91 to 1.12.
Homologues: Orthologues: chimpanzee FICD (99% identical), macaque FICD (98% identical), dog FICD (94% identical), pig FICD (92% identical), guinea pig FICD (91% identical), rat Ficd (90% identical), mouse Ficd (90% identical), rabbit FICD (87% identical), tropical clawed frog ficd (72% identical), zebrafish ficd (68% identical), Drosophila melanogaster Fic (46% identical), Caenorhabditis elegans fic-1 (38% identical).
Diseases named in the same sentence as FICD in open-access papers:
FICD is named in the same sentence as 17 diseases in open-access papers, as found by Europe PMC text mining. Sharing a sentence is not in itself a finding about the gene and the disease. The quoted sentences say what the papers report.
cervical carcinoma (2 papers, 2021 to 2025). A carcinoma arising from either the exocervical squamous epithelium or the endocervical glandular epithelium. "The remaining 10 genes (i.e., YJEFN3, SPATA5L1, C5orf55, PPM1A, IMMP1L, ZNF330, PPIP5K2, ESCO2, FICD, and ZNF225) are not directly reported to be related to the survival risk of cervical cancer in previous literature." (PMID 34149809, 2021).
cataract (1 paper, 2025). Partial or complete opacity of the crystalline lens of one or both eyes that decreases visual acuity and eventually results in blindness. "Because FicD regulates UPR signaling though BiP, additional physiological or chronic stressors may reveal phenotypes in other affected tissues, such as growth defects, neurodevelopmental delays, and cataracts seen in human patients." (PMID 40073934, 2025).
depression (1 paper, 2024). "Whole-exome sequencing (WES) identified the variant c.1295C>T (p.Ala432Val) in the FICD gene in a patient presenting with borderline intellectual functioning, acanthosis, depression, obesity tendencies (BMI 34), and optic nerve subatrophy." (PMID 39766922, 2024).
diabetes (1 paper, 2025). "In this study, we developed a preclinical mouse model for neonatal diabetes based on the hFicDR371S mutation identified in humans, which disrupts FicD-mediated deAMPylation of BiP, impairing its regulatory function." (PMID 40073934, 2025). "Understanding how FicD dysfunction contributes to β-cell failure may uncover novel therapeutic approaches for ER stress-related diabetes and metabolic diseases." (PMID 40073934, 2025).
hereditary spastic paraplegia (1 paper, 2024). Hereditary spastic paraplegias (HSP) comprise a genetically and clinically heterogeneous group of neurodegenerative disorders characterized by progressive spasticity and hyperreflexia of the lower limbs. "The current study aimed to expand the phenotypic spectrum associated with the FICD gene, which has previously been linked to hereditary spastic paraplegia (HSP) with the MIM phenotype number 620911." (PMID 39766922, 2024).
Spastic paraplegia (1 paper, 2024). Complete loss of the ability to move the lower limbs accompanied by spasticity of the lower limbs. "The FICD gene is annotated in the OMIM database for spastic paraplegia 92 (MIM phenotype entry code #620911), with an autosomal recessive (AR) inheritance pattern." (PMID 39766922, 2024).
FICD also shares sentences with these, for which no sentence is quoted: breast carcinoma (1 paper); cancer (1); gastric cancer (1); hepatocellular carcinoma (1); melanoma (1); metabolic disease (1); non-small cell lung carcinoma (1); Obesity (1); osteosarcoma (1); ovarian carcinoma (1); prostate carcinoma (1).